ANKRD20A5P (ankyrin repeat domain 20 family member A5, pseudogene)
Synonyms: MGC26718; formerly ANKRD20A5
Gene: Transcribed unprocessed pseudogene on chromosome 18 (14,179,395 to 14,244,811, forward strand). Ensembl gene ENSG00000186481.
Diseases named in the same sentence as ANKRD20A5P in open-access papers:
ANKRD20A5P is named in the same sentence as 1 disease in open-access papers, as found by Europe PMC text mining. Sharing a sentence is not in itself a finding about the gene and the disease.
ANKRD20A5P shares sentences with these, for which no sentence is quoted: cancer (1 paper).